CD24 (CD24 molecule)
Diseases named in the same sentence as CD24 in open-access papers (continued):
Sharing a sentence is not in itself a finding about the gene and the disease.
ovarian serous carcinoma (2 papers, 2021). "Another study assessed the protein expression of E-CADH, N-CADH, P-cadherin, ZEB1, HMGA2, RAB25, CD24, NCAM, SOX11, and VIM in 100 tubo-ovarian serous carcinoma effusions and found a limited prognostic role of the markers alone or in combination." (PMID 34070214, 2021).
Parkinson disease (2 papers, 2017 to 2021). A progressive degenerative disorder of the central nervous system characterized by loss of dopamine producing neurons in the substantia nigra and the presence of Lewy bodies in the substantia nigra and locus coeruleus. "The role of CD24 was also examined in a mouse model of Parkinson’s disease." (PMID 33562144, 2021). "Likewise, Parkinson’s disease, which is also investigated in relation to CD24, is known to result in some cognitive decline." (PMID 33562144, 2021).
renal fibrosis (2 papers, 2024 to 2025). A final common manifestation of a wide variety of chronic kidney diseases characterized by glomerulosclerosis and tubulointerstitial fibrosis. "CD24+ progenitors have been shown to repair kidney injury and reverse renal fibrosis in experimental animals and even in humans." (PMID 39872151, 2024).
salivary duct carcinoma (2 papers, 2013 to 2024). An aggressive, high grade adenocarcinoma that arises from the salivary glands. "A few studied cases of salivary duct carcinoma (SDC) were positive for CD24 and CD44, while almost all cases were negative for c-KIT." (PMID 39858584, 2024).
seminoma (2 papers, 2022 to 2024). A radiosensitive malignant germ cell tumor found in the testis (especially undescended), and extragonadal sites (anterior mediastinum and pineal gland). "Similar observations were found in a cohort of 24 GCT patient samples, where CD24 was predominantly upregulated in non‐seminoma compared with seminoma." (PMID 34293822, 2022). "93% of ECs were CD24+, while only 15% of seminoma cell components in mixed GCT setting and 18% of pure seminomas were CD24+." (PMID 34293822, 2022). "We asked how CD24 expression is affected during differentiation of EC cells and during reprogramming of seminoma‐like TCam‐2 cells into an EC‐like cell fate." (PMID 34293822, 2022). "We also checked whether SOX17, which in part shows redundancy to SOX2 in regulating pluripotency in seminomas, binds to CD24 as well." (PMID 34293822, 2022). "In GCTs, each analyzed entity displayed an individual marker expression profile, with ECs mainly presenting as CD24strong/CD44+/CD133+/CD184‐, seminomas as CD24‐/CD44+/CD133+/CD184+, YSTs as CD24weak/CD44‐/CD133‐/CD184+, and CCs as CD24weak/CD44‐/CD133‐/CD184‐." (PMID 34293822, 2022). "In the SOX17+/SOX2‐/CD24‐ seminoma cell line TCam‐2, only negligible binding intensities of SOX17 to CD24 could be detected (peak intensities < 15)." (PMID 34293822, 2022). "In GCTs, CD24 (isoform ENST00000606017.1) is strongly expressed in ECs and absent to very weakly expressed in germ cells of different developmental stages, seminomas, YSTs, and CCs." (PMID 34293822, 2022). "Next, we stained GCNIS (n = 46), seminoma (n = 74), EC (n = 27), YST (n = 15), and CC (n = 3) tissues for CD24 by IHC." (PMID 34293822, 2022). "Thus, we hypothesize that in GCT entities resembling (primordial) germ cells (GCNIS, seminoma), CD24 is absent, allowing for expression of germ cell factors, while in embryonal stem cell‐like ECs, which show the least relationship to germ cells, CD24 is involved in blocking the germ cell program." (PMID 34293822, 2022).
spindle cell carcinomas (2 papers, 2008 to 2015). "Histological examination of tissue sections reveals that unsorted SUM159 cells form highly invasive spindle-cell carcinomas, and this spindle-cell morphology is recapitulated in SUM159 tumors derived from 1 × 103 CD44+/CD24-/low/ESA+ cells." (PMID 18366788, 2008).
T-Cell Lymphoma (2 papers, 2017 to 2018). "In T-cell lymphoma, TEXs bearing the marker of malignancy CD24 and HSP-70elicited specific immune responses and immune memory that allowed the rejection of subsequent tumor challenges." (PMID 30103789, 2018). "It was reported that T-cell lymphoma TEXs contain tumor antigens CD24 and HSP-70." (PMID 30103789, 2018).
tuberculosis (2 papers, 2022 to 2023). A chronic, recurrent infection caused by the bacterium Mycobacterium tuberculosis. "A subset of immature transient CD24++CD38+ B-cells performs diverse regulatory functions, the elevation of which was detected in tuberculosis patients compared to healthy subjects." (PMID 37626620, 2023).
type 2 diabetes (2 papers, 2023). "Interestingly, CD24 was also up-regulated in the NAFLD patients with type 2 diabetes than its expression in non-diabetic cases, but without significant difference." (PMID 36900128, 2023).
abortion (1 paper, 2024). the ending of pregnancy by removing a fetus or embryo before it can survive outside the uterus. "Notably, Results from the B cell group showed a positive correlation between abortion and certain phenotypes, including Unsw mem %B cell, PB/PC %B cell, IgD+ CD24+ %B cell and Naive-mature B cell %lymphocyte." (PMID 39388432, 2024).
acute pancreatitis (1 paper, 2016). An acute inflammatory process that leads to necrosis of the pancreatic parenchyma. "Such hypothesis is further supported by the upregulation of CD24 during acute pancreatitis in concomitance to inhibition of Notch1-dependent β-catenin transcriptional activity by DBZ treatment." (PMID 27203385, 2016). "Intriguingly, we observe strong intracellular CD24 expression in concomitance with cytoplasmic β-catenin both in PDAC and acute pancreatitis mouse models." (PMID 27203385, 2016). "In this study, we focus on the function of CD24 in genetically engineered mouse models (GEMM)-based endogenous PDAC and in cerulein-induced experimental acute pancreatitis." (PMID 27203385, 2016). "In this study we investigate the function of CD24 using GEMM of endogenous PDAC and a model of cerulein-induced acute pancreatitis." (PMID 27203385, 2016).
adenoid cystic carcinoma (1 paper, 2013). A malignant tumor arising from the epithelial cells. "On the other hand Ma and colleagues reported that metastatic adenoid cystic carcinoma cell lines lack CD24 expression." (PMID 23419168, 2013).
bone marrow disorder (1 paper, 2025). Any disease of the bone marrow. "Six patients had classical PNH with hemolytic anemia and large PNH clones (> 60% neutrophils [FLAER/CD24] and monocytes [FLAER/CD14), three had PNH with small clones (< 10% granulocytes and monocytes) in the context of another bone marrow disorder, and one had subclinical PNH with a clone size < 1%." (PMID 40886199, 2025).
cardiac arrest (1 paper, 2025). Cessation of breathing and/or cardiac function. "Further large-scale studies are warranted to validate these findings and to elucidate the functional role of the CD24/Siglec-10 axis in post-cardiac arrest patients." (PMID 41162542, 2025). "We aimed to study serum biomarkers in CD24/Siglec-10 axis and explore their associations with the survival and neurological prognosis of patients after return of spontaneous circulation (ROSC) following cardiac arrest." (PMID 41162542, 2025).
cardiomyopathy (1 paper, 2021). A disease of the heart muscle or myocardium proper. "Furthermore, the most substantial differences were found in the augmentation of CD24+CD27+ in G0 and NI, together with a drop in the frequency of and CD27−CD38+ B cells in CCD patients with cardiomyopathy." (PMID 34458163, 2021). "Isolated B cells from CCD patients with or without cardiomyopathy and non-infected (NI) donors were stimulated with T. cruzi lysate or CpG + CD40L, and characterized by flow cytometry based on the expression of CD24, CD27, CD38, and the regulatory molecules IL-10 and PD-L1." (PMID 34458163, 2021).
chronic atrophic gastritis (1 paper, 2017). Atrophic gastritis that is persistent and long-standing. "Wang and his colleagues reported that CD24 expression increased gradually in samples of normal gastric mucosa, non-atrophic chronic gastritis, chronic atrophic gastritis (CAG), CAG with intestinal metaplasia, dysplasia and GC." (PMID 28968998, 2017).
chronic leukemia (1 paper, 2021). A slowly progressing leukemia characterized by a clonal (malignant) proliferation of maturing and mature myeloid cells or mature lymphocytes. "scATAC-seq, used to identify co-varying transcription factor-cell surface marker pairs, was combined with scRNA-seq for cell surface marker expression to detect efficiently CD24-labeled chronic leukemia cells as co-varying with chromatin accessibility changes linked to GATA transcription factors." (PMID 33785068, 2021).
crescentic glomerulonephritis (1 paper, 2018). A histopathologic term for a pattern of diseases characterized by extensive crescent formation in the glomeruli; patients present clinically with rapid deterioration of renal function, and possible progression to end-stage renal failure within weeks or months. "In crescentic glomerulonephritis, CD24+ CD133+ proliferating cells constitute the major contingent of the hyperplastic lesions whereas podocytes included in these lesions do not proliferate." (PMID 30439969, 2018).
cystic tumor (1 paper, 2016). "One out of three mice developed a cystic tumor from 4000 non-CD24+CD90+ tumor cells." (PMID 27542270, 2016).
disc degeneration (1 paper, 2018). "Having established the progenitor properties and having delineated the protective effect of CD24-positive NP cells against disc degeneration, we next sought to investigate the underlying mechanisms that regulate differentiation of CD24-positive NP cells." (PMID 30598696, 2018). "Taken together, these data proved that transplantation of CD24-positive NP cells alleviated disc degeneration." (PMID 30598696, 2018). "In the present study, we found that the proportion of CD24-positive NP cells significantly decreased with increasing severity of disc degeneration." (PMID 30598696, 2018). "Here, we found that the number of CD24-positive NP cells significantly decreased with increasing severity of disc degeneration." (PMID 30598696, 2018). "Having established the notochordal/progenitor properties of CD24-positive NP cells, we next evaluated the therapeutic effect of CD24-positive NP cells on disc degeneration." (PMID 30598696, 2018). "To investigate the clinical relevance of CD24-positive NP cells for disc degeneration, we first measured the abundance of CD24-positive cells in human NP tissues isolated from degenerated IVDs." (PMID 30598696, 2018). "By contrast, with increasing severity of disc degeneration, CD24 expression decreased dramatically." (PMID 30598696, 2018). "Subsequent quantitative analysis of disc degeneration severity by MRI indicated a strong increase in the gray value of discs under the influence of transplantation of CD24-positive NP cells, observed as more hypointense signals in the midsagittal T2-weighted images." (PMID 30598696, 2018). "Therefore, CD24 might be a suitable marker of NP progenitor/notochordal cells; moreover, transplantation of CD24-positive NP cells might exert a promising therapeutic effect on disc degeneration." (PMID 30598696, 2018). "Our findings uncovered a vital protective role of CD24-positive NP cells against disc degeneration and revealed that HIF-1α-NOTCH1 pathway activation is essential for the maintenance of CD24-positive notochordal cells." (PMID 30598696, 2018). "The NP tissue of the rat lumbar IVD was punctured with a 21-gauge needle to induce disc degeneration and was injected with PBS, unsorted NP cells, or CD24-positive NP cells." (PMID 30598696, 2018). "Taken together, these results indicated that CD24-positive cells in NP showed a negative relation to disc degeneration." (PMID 30598696, 2018).
duodenitis (1 paper, 2021). Acute or chronic inflammation of the duodenum. "In our study, only one malnourished adult, who also fell in the category of specific duodenitis, was found positive for CD, and the IEL count, which is a key histopathologic marker of CD24, was also insignificant in the studied population." (PMID 33504937, 2021).
end stage renal disease (1 paper, 2014). "At variance, the levels of EVs expressing the renal exosomal marker CD24 did not vary in the urine of patients with end stage renal disease or in transplanted patients in respect to controls." (PMID 25100147, 2014). "The reduction of urinary CD133+ EV levels but not of CD24+ EVs in end stage renal disease indicates that these vesicles are only released by functioning renal tissue, suggesting an exhaustion of the progenitor activity that parallels the loss of kidney function." (PMID 25100147, 2014).
epithelial ovary cancer (1 paper, 2014). "In epithelial ovary cancer cells, stem-like CD24- cells or spheroids highly expressed cyclin D1, Bmi-1, and vimentin with reduced expression of E-cadherin, while non stem-like CD24+ or parental cells showed the opposite expression." (PMID 25477004, 2014).
esophageal tumor (1 paper, 2017). "Moreover, we found that esophageal tumor cells exhibited heterogeneous CD24 protein expression, suggesting the presence of different populations or cells with different differentiation states within the EAC cell culture." (PMID 28611669, 2017).
fetal growth restriction (1 paper, 2021). A fetus that does not grow beyond the 10th percentile of conventionally accepted weight for gestational age. "Therefore, CD24 reduction in early PE may be linked to increased rejection of the placenta, and its reduced expression may be associated with early cases of PE and could be relevant to cases also complicated by fetal growth restriction." (PMID 34360811, 2021).
gastric cardia carcinoma (1 paper, 2025). A carcinoma that arises from epithelial cells of the cardia of stomach. "For instance, CD24+CD44+EpCAM+ gastric CSCs are significantly associated with poor patient prognosis, and the NNMT+/AQP5+ phenotype could serve as a potential diagnostic marker for gastric cardia cancer." (PMID 40665579, 2025).
generalized anxiety disorder (1 paper, 2023). An anxiety disorder characterized by excessive and difficult-to-control worry about a number of life situations. "By FDR correction (PFDR<0.05), we found two immunophenotypes to be protective against generalized anxiety disorder: CD24+CD27+B cells and CD28+CD4+T cells." (PMID 38264647, 2023).
gout (1 paper, 2024). A condition characterized by painful swelling of the joints, which is caused by deposition of urate crystals. "Among them, 2 immunophenotypes (CD4-CD8-T cell absolute count and CD25 on IgD + CD24 + B cell) increased the risk of developing gout, whereas the other one immunophenotype (CD45RA + CD28- CD8 + T cell %T cell) decreased the risk of gout." (PMID 39432655, 2024). "Additionally, we have identified CD25 on IgD CD24 B cells as a risk factor for the development of gout." (PMID 39432655, 2024). "Based on our study, an increased CD25 on IgD + CD24 + B cell and CD4-CD8- T cell absolute count are associated with a higher risk of gout occurrence." (PMID 39432655, 2024). "CD25 on IgD + CD24 + B cell (OR = 1.059, 95% CI = 1.025–1.095, P = 6.32e-4, PFDR = 0.154) increased the risk of gout, and the other 4 methods also indicated it was a risk factor." (PMID 39432655, 2024).
Hereditary breast cancer (1 paper, 2008). Breast carcinoma that has developed in relatives of patients with history of breast carcinoma. "We demonstrate an association between basal-like and particularly BRCA1 hereditary breast cancer and the presence of CD44+/CD24- cells." (PMID 18559090, 2008).
hypercoagulation (1 paper, 2021). "Higher CD24 staining in PE at term might be linked to hypercoagulation and may indicate a potential difference in the underlying pathways." (PMID 34360811, 2021).
hyperplasia (1 paper, 2016). An abnormal increase in the number of cells in an organ or a tissue with consequent enlargement. "In human prostates, CD24 expression was similarly found to be frequently present in atrophic glands and intraepithelial neoplasia, and clearly upregulated in atypical epithelia, whereas it is rare in non-neoplastic tissue and benign hyperplasias." (PMID 26978528, 2016).
IgG4-related diseases (1 paper, 2024). "For IgG4-related diseases, the peripheral blood was significantly enriched in B cell populations, including CD19+ CD24-CD38hi PB/PC." (PMID 38706698, 2024).
ischemia (1 paper, 2011). A hypoperfusion of the BLOOD through an organ or tissue caused by a PATHOLOGIC CONSTRICTION or obstruction of its BLOOD VESSELS, or an absence of BLOOD CIRCULATION. "We also tested the ability of CD184−/CD44−/CD15LOW/CD24+ neurons to engraft in spinal ischemia-injured rats (data not shown)." (PMID 21407814, 2011).
leprosy (1 paper, 2021). Leprosy is a chronic infectious disease affecting primarily the skin and peripheral nervous system. "We observed a reduced frequency in patients with MB leprosy and with ENL both in total B cells (CD19+) and in memory cells (CD19+CD24+CD38+/-)." (PMID 34621273, 2021).
liver dysfunction (1 paper, 2023). "Here, the proliferative activity of the resident LPCs was activated by the cocktail (CD24+LCN2+ LPCs), and their phenotypes and roles in liver dysfunction was characterized together with those of hepatocyte-derived LPCs (HepLPCs) and BEC-derived LPCs (BecLPCs)." (PMID 37784089, 2023).
lymphedema (1 paper, 2026). Excess fluid collection in tissues, causing swelling. "To date, mutations in Cd24 have not been associated with valve defects or lymphedema in either species." (PMID 41186588, 2026).
lymphoid leukaemia (1 paper, 2024). "IgD on IgD+ CD24- mediated the causal relationship between 1-palmitoyl-GPE (16:0) and lymphoid leukaemia (Mediated proportion = -13% [-1.24%,-24.7%])." (PMID 39351228, 2024).
malnutrition (1 paper, 2012). Inadequate nutrition resulting from poor diet, malabsorption, or abnormal nutrient distribution. "The analysis of BM B cell subsets based on B220, CD24, IgM and IgD expression showed that malnutrition affected B cell development." (PMID 22347448, 2012).
mesenchymal tumors (1 paper, 2010). "Five genes were significantly differentially expressed in chordoma tumors compared with three control groups (nonchordoma mesenchymal tumors, normal tissues, and IVD): T, CD24, COL2A1, CA3, and KRT19." (PMID 21253487, 2010).
mucinous ovarian cancer (1 paper, 2025). An invasive malignant neoplasm that arises from the ovary and is characterized by the presence of malignant epithelial cells that contain intracytoplasmic mucin and may resemble the epithelial cells of the endocervix or gastrointestinal tract. "A study found that mucinous ovarian cancer (MOC) with infiltrative invasion was more often positive for CK5/6, CD24, and EGFR, suggesting that these markers may be linked to the aggressive features of this invasion pattern." (PMID 40231265, 2025).
Myalgic Encephalomyelitis (1 paper, 2018). "We recently described significantly increased frequency and expression of CD24 on subsets of IgD+IgM+ B cells from patients suffering from Myalgic Encephalomyelitis/Chronic Fatigue Syndrome (ME/CFS), a multisystem disorder characterized by fatigue, post-exertional malaise and cognitive impairment." (PMID 30405620, 2018). "We previously detected higher CD24 expression and frequency within IgD+ naïve and memory B cells in patients with Myalgic Encephalomyelitis/Chronic Fatigue Syndrome (ME/CFS) compared with age-matched healthy controls (HC)." (PMID 30405620, 2018).